STAT3 (signal transducer and activator of transcription 3)
Diseases named in the same sentence as STAT3 in open-access papers (continued):
Sharing a sentence is not in itself a finding about the gene and the disease.
liver fibrosis (continued). "This indicates that inhibition of the STAT3 pathway under these pro-inflammatory conditions will combat hepatic fibrosis, which is consistent with our results." (PMID 29795016, 2018). "Previous studies also found that STAT3 activation in hepatocytes and hepatic stellate cells lead to hepatic fibrosis." (PMID 29615085, 2018). "The current study represents the first report that highlights the inhibitory effect of BM-MSCs on IL6/STAT3 pathway in liver fibrosis." (PMID 30346985, 2018). "Multiple studies have demonstrated that apoptosis of activated HSCs results in accelerated recovery from liver fibrosis and work from our lab has confirmed that inhibition of STAT3 results in HSC apoptosis." (PMID 29795016, 2018). "Murine models involving carbon tetrachloride induced fibrosis have demonstrated that STAT3 activation prevents hepatic fibrosis, while activation of STAT3 in the dimethylnitrosamine induced fibrosis model promotes fibrosis." (PMID 29795016, 2018). "It was reported that kahweol induces apoptosis in cancer cells by decreasing the STAT3 levels and in turn inhibits hepatic fibrosis in the liver." (PMID 29973533, 2018). "IL-6 is a pleiotropic cytokine in modulating inflammatory responses in liver diseases through activation and phosphorylation of both NF-κB and STAT3 proteins, which in turn stimulate progressive liver fibrosis." (PMID 29179490, 2017). "Altogether, these findings indicate that the phosphorylation of STAT3 mediates the IL-17A-suppressed autophagy of hepatocytes, which is involved in the development of hepatic fibrosis." (PMID 28039485, 2017). "The inhibitory effect of kahweol on hepatic fibrosis was associated with downregulation of TGF-β-stimulated phospho-Smad3, STAT3, ERK, and JNK expression." (PMID 29152065, 2017). "Our study indicates that antagonism of IL-17A attenuates liver fibrosis by restoring the STAT3-suppressed autophagy flux in the BDL-and TAA-induced fibrotic liver tissues." (PMID 28039485, 2017). "Taken together, these findings indicate that IL-10/STAT3 activation mediates IL-17A-suppressed autophagy and participates in the development of hepatic fibrosis." (PMID 28039485, 2017). "The interaction between IL-22/STAT3 and Wnt/β-catenin pathway is involved in the development of hepatic fibrosis in vivo." (PMID 27819314, 2016). "In this study, the effects of PL on the regulation of EGFR and STAT3 were investigated in carbon tetrachloride (CCl4) induced liver fibrosis and hepatic stellate cells (HSC-T6)." (PMID 26550019, 2015). "Epidermal growth factor (EGF) and its signaling molecules, EGFreceptor (EGFR) and signal transducer and activator of transcription factor 3 (STAT3), have been considered to play a role in liver fibrosis and cirrhosis." (PMID 26550019, 2015). "Taken together, there is emerging evidence that supports a significant role of Stat3 in stimulating liver fibrosis." (PMID 22973518, 2012). "More recent studies have demonstrated key roles for other pathways, including TLR4 and Jak/Stat3 in hepatic fibrosis." (PMID 22973518, 2012). "Additionally, further analysis revealed a positive correlation between MCM7 expression and STAT3 phosphorylation in murine liver fibrosis models." (PMID 40789837, 2025). "Although some studies suggest that it may inhibit viral replication, others indicate that it contributes to liver fibrosis, potentially through activation of STAT3, a transcription factor involved in the proliferation and survival of hepatic stellate cells." (PMID 41465470, 2025). "In contrast, in another study, it was shown that ruxolitinib targeted and inhibited the STAT3 upstream kinase Janus kinase 1/2, which could inhibit the progression of carbon tetrachloride (CCl4)–induced liver fibrosis in mice." (PMID 40368138, 2025).
liver fibrosis (continued). "Ssb1 prevented liver fibrogenesis in the TAA and CCl4‐induced animal models by suppressing STAT3 activation and blocking STAT3/Gli1 interaction, and specific knockdown of STAT3 in mice liver further strengthened the critical role of STAT3 in the Ssb1 treatment of liver fibrosis." (PMID 41163803, 2025). "Furthermore, the continuous activation of STAT3 can also upregulate the activity of hepatic stellate cells (HSCs), which paves the way for the development of liver fibrosis." (PMID 41377803, 2025). "In summary, this study identified Ssb1 as a novel STAT3 inhibitor in liver fibrosis treatment." (PMID 41163803, 2025). "S3I‐201 was adopted as a positive control to inactive STAT3 in liver fibrosis." (PMID 41163803, 2025). "These fibrinogens may foster HSCs activation by binding to integrin αvβ3/5 on HSCs’ membranes, suggesting the POFUT1/NOTCH/HES1/STAT3/fibrinogen axis as a novel therapeutic strategy of liver fibrosis." (PMID 40761743, 2025). "Additionally, IL-6 induces HSCs activation and liver fibrosis via the Janus Kinase/Signal Transducer and Activator of Transcription 3 (JAK/STAT3) signaling pathway." (PMID 39995661, 2025). "In brief, the current work showed that PZH may act as a therapeutic agent for liver fibrosis by inhibiting the EGFR/JAK1/STAT3 signaling axis and macrophage M1 polarization." (PMID 41181146, 2025). "In the presence of inflammation, interleukin-6 (IL-6) could activate janus kinase 2 (JAK2)-signal transducer and activator of transcription 3 (STAT3) signaling pathway of which has been reported to lead to liver fibrosis." (PMID 41293246, 2025). "Therefore, targeting JNK and STAT3 by Tenovin-1 inhibits this activation of HSCs, hence, decreases hepatic fibrosis." (PMID 38993557, 2024). "However, additional studies will have to be performed to characterize the mechanism(s) by which the Wnt/β-catenin and p38 MAPK pathways, along with the SMAD and STAT3 pathways that are also activated by TGFBRs and PDGFBRs, jointly contribute to liver fibrosis." (PMID 39656528, 2024). "Activation of STAT3 can play pro-inflammatory roles in the pathogenesis of liver fibrosis." (PMID 38699038, 2024). "Furthermore, Masson’s trichrome staining demonstrated collagen accumulation in DDC + Veh mice, whereas collagen expression decreased in DDC + STAT3 mice, suggesting that DDC-induced liver fibrosis was regulated by STAT3 decoy ODN." (PMID 38338338, 2024). "The involvement of STAT3 in HFD-induced liver fibrosis was investigated by western blotting." (PMID 38993557, 2024). "When fibrosis is driven by PDGFRβ/STAT3 pathway activation — as occurs in ARPKD liver fibrosis or in murine models of lung and bone marrow fibrosis — PDGFR inhibitors exhibit antifibrotic efficacy but are less effective when the fibrosis is driven by other mechanisms." (PMID 39656528, 2024). "By combining transcriptome analysis with network pharmacology analysis, we demonstrated that the therapeutic mechanism of XYS in NASH-related liver fibrosis involves the regulation of STAT3, NFκB, and PPARγ and their downstream genes and the intervention of the ECM, inflammation, and metabolism." (PMID 39338294, 2024). "miR-148a from MSC-derived exosomes prevents liver fibrosis by targeting KLF6/STAT3 pathway." (PMID 38756248, 2024). "Whereas other findings support a protective effect of STAT3 on hepatic fibrosis." (PMID 36671504, 2023). "However, it is challenging to develop highly potent and selective inhibitors of STAT3 against the liver fibrosis." (PMID 37978263, 2023). "This might be regulated by TF Hlf, which facilitates liver fibrosis through activation of HSCs driven by the HLF/IL-6/STAT3 feedforward circuit." (PMID 36814339, 2023). "A gene cluster that was significantly downregulated in the Yap/Wwtr1 knockdown group contained genes primarily regulated by Tgfβ-1 and related to “hepatic fibrosis”, Stat3 pathway, and Th2 pathway— illustrating suppression of pro-fibrotic genes with depletion of Yap and Wwtr1." (PMID 36998974, 2023).
liver fibrosis (continued). "Therefore, we identified Sa32 as the best small molecule potent inhibitor for STAT3 that will be helpful in the future for the treatment of liver fibrosis." (PMID 37978263, 2023). "Currently, most studies suggest that STAT3 mainly plays a role in promoting hepatic fibrosis, and its expression level may be positively correlated with the degree of fibrosis." (PMID 38074679, 2023). "However, the effect of DAU on the activation of STAT3 showed that it has the potential to improve liver fibrosis." (PMID 36615880, 2023). "A recent study reveals that the expression of C-myc and Smad2/3 are upregulated in LPS-treated hepatic stellate cells, while the expression of recombinant thrombospondin 1 and phosphorylation of STAT3 is upregulated in the hepatocytes of mice with liver fibrosis." (PMID 36986363, 2023). "It is shown that saffron can alleviate liver fibrosis by inhibiting the JAK/STAT3 pathway." (PMID 38055395, 2023). "Loss of STAT5 in hepatocytes enhanced GH-induced STAT3 activity and increased TGF-β levels after CCl4 intervention, and STAT5 deficiency also increased the sensitivity of Kupffer or hepatic stellate cells to TGF-β and pro-hepatic fibrosis." (PMID 36671504, 2023). "Based on the present study, it could be concluded that lycorine hinders TAA-induced liver fibrosis in rats, due to—at least partly—its antioxidative and anti-inflammatory properties along with its ability to inhibit STAT3 signaling." (PMID 35337166, 2022). "This signature revealed potential immune therapeutic targets (STAT3) to ameliorate liver fibrosis." (PMID 35052861, 2022). "sIRNAs or ASO targeting STAT3 was packaged into clinical grade fibroblast-like MSC-derived EVs by electroporation significantly downregulated STAT3 levels as well as improved liver function in liver fibrosis mice." (PMID 35915850, 2022). "IPA of MYOC/CCL19 fibroblast gene expression correlating with the mRSS revealed several prominent pathways: senescence, hepatic fibrosis signaling, IL-6 signaling, STAT3 signaling, TGF-β signaling, protein ubiquitination, JAK/Stat signaling, and role of JAK1, JAK2 and TYK2 in interferon signaling." (PMID 35943798, 2022). "We assumed that the ERβ overexpression could affect the expressions of multiple downstream genes related to liver fibrosis by activating STAT3." (PMID 36207725, 2022). "Furthermore, it was observed that the levels of Acta2, Col1a1, Col3a1, Tnfa, Il6, and Il1β genes were significantly increased upon STAT3 overexpression, again suggesting that STAT3 mitigated liver fibrosis." (PMID 36588728, 2022). "Liu X Showed that scoparone could inhibit the transforming growth factor-β (TGF-β)/Smad/Stat3 signaling pathway, therefore inhibiting the proliferation of hepatic stellate cells and significantly reducing liver fibrosis." (PMID 35592421, 2022). "However, the levels of the fibrosis marker α-SMA were significantly increased upon STAT3 overexpression, suggesting that STAT3 mitigated liver fibrosis." (PMID 36588728, 2022). "The existing reports suggests that STAT3 plays an important role in the development of liver fibrosis and demonstrates that STAT3 selective inhibitors can effectively attenuate the progression of liver fibrosis." (PMID 35382859, 2022). "In addition, H2S can inhibit the activation of Stat3 to attenuate TGF-β1 signaling involving the improvement of liver fibrosis." (PMID 34645391, 2021). "Umbilical-cord-derived MSCs and also allogenic ABCB5-positive MSCs that improve liver fibrosis enhance regeneration, suppress inflammation, and downregulate Notch and Stat1/Stat3 signaling in rats are under clinical trials (NCT04822922, NCT03860155) for the treatment of patients with ACLF." (PMID 34820395, 2021). "In addition, it was shown that, upon deletion of STAT3 in hepatocytes, there is an exacerbation of liver fibrosis during cholestasis." (PMID 34047814, 2021).
liver fibrosis (continued). "In addition, upregulation of Stat3 has been shown to have both anti- and pro-inflammatory roles during the pathogenesis of liver fibrosis." (PMID 34428250, 2021). "In the fibrotic liver, JAK2/STAT3 pathway is also able to influence liver fibrosis." (PMID 35432812, 2021). "As crosstalk between SMAD3 and STAT3 in numerous biological functions is well documented, and because TGFβ1 can activate STAT3, which also has a role in liver fibrosis, we hypothesized that STAT3 may contribute to the antifibrotic effects of rottlerin." (PMID 32210801, 2020). "STAT5 could directly bind to TGF-β through its N-terminal sequences and decreased TGF-β protein stability, suggesting a role of STAT5-TGF-β-STAT3 axis in liver fibrosis." (PMID 32708044, 2020). "The HLF/IL‐6/STAT3 feed forward circuit could induce the activation of HSCs, resulting in liver fibrosis." (PMID 32306539, 2020). "Furthermore, JAK2/STAT3 pathway–related autophagy was also identified as a potential therapeutic target for hepatic fibrosis in our study." (PMID 32233073, 2020). "Our study showed, for the first time, the inhibitory effects of C8G from R. palmatum on HSC activation through inhibition of the STAT3 pathway, which is a key therapeutic target in hepatic fibrosis, thus providing experimental evidence for the hepatoprotective effects of C8G against liver damage." (PMID 33261209, 2020). "Our previous study found that fructose up‐regulated p‐STAT3 in rat liver fibrosis." (PMID 33058500, 2020). "Now that STAT3 appeared to be essential in recruiting MKL1 to activate Twist1 transcription, we tested the hypothesis that STAT3 inhibition might serve to attenuate liver fibrosis." (PMID 31776330, 2019). "In a rat model of hepatic fibrosis and mouse hepatic stellate cells, ADSC-Exos could activate cell autophagy and reduce TGF-β1-induced hepatic fibrosis via suppressing the STAT3/Bcl-2/Beclin1 pathway." (PMID 31391108, 2019). "STAT3 may promote hepatic fibrosis through the upregulation of tissue inhibitor of metalloproteinases-1 and transforming factor-ß expression." (PMID 29615085, 2018). "Collectively, we suggest that BM-MSCs might play an immunomodulatory role in the treatment of liver fibrosis through downregulation of IL17A affecting IL6/STAT3 signaling pathway." (PMID 30346985, 2018). "The role of STAT3 is controversial in mediating signaling of liver fibrosis." (PMID 30346985, 2018). "The overexpression of STAT3 in hepatic fibrosis may have model-dependent and cell-specific functions." (PMID 29795016, 2018). "In the present study, we evaluated the capacity of the BM-MSCs in the modulation of cytokines milieu and signal transducers, based on unique inflammatory genes Il17a and Il17f and their receptors Il17rc and their effect on the IL6/STAT3 pathway in CCl4-induced liver fibrosis in rats." (PMID 30346985, 2018). "Interleukin 6 (IL6) stimulates the activation of STAT3 and increases collagen mRNA expression in HSCs, thus accelerating liver fibrosis via Stat3 phosphorylation that in turn activates transforming growth factor beta (TGFβ) signaling cascade through SMAD3 activation." (PMID 30346985, 2018). "Thus, we suggest that BM-MSCs ameliorate liver fibrosis via downregulation of IL17A dependent IL-6/STAT3 signaling pathway." (PMID 30346985, 2018). "Importantly, deletion of EGFR phenocopied deletion of STAT3 and led to aggravated liver damage, liver fibrosis, and hyperproliferation of K19+ cholangiocytes." (PMID 27568040, 2017). "In current study, we further find that IL-17A inhibits autophagy via the activation of STAT3, which may hinder the degradation of collagen and the clearance of injured tissue debris and interfere with the resolution of hepatic fibrosis." (PMID 28039485, 2017).
liver fibrosis (continued). "In summary, our current study not only indicates the IL-17A/STAT3 pathway playing a critical role in the pathogenesis of hepatic fibrosis, but also provides the proof of concept for this pathway acting as a potential therapeutic target against hepatic fibrosis." (PMID 28039485, 2017). "We concluded that IL-22 inhibits HSC activation and ameliorates liver fibrosis through enhancing expression of miR-200a and reducing expression of β-catenin, suggesting there may be a crosstalk between IL-22/STAT3 and β-catenin pathway." (PMID 27819314, 2016). "In the hepatic fibrosis mouse model the role of STAT3 on senescence in activated HSCs has studied." (PMID 27468691, 2016). "Therefore, we set out to investigate the precise role of the STAT3 pathway on liver fibrosis in human activated HSCs." (PMID 27489164, 2016). "We further identified the inverse association between expression of STAT3 and β-catenin in HSC, indicating there may have a cross-talk between IL-22/STAT3 and Wnt/β-catenin signaling pathways in development of liver fibrosis." (PMID 27819314, 2016). "Therefore, the current study investigated the effect of PL on liver fibrosis in a rat fibrotic liver model as well as in HSC-T6 cells and explored the possible underlying mechanisms of liver fibrosis, particularly the EGFR/STAT3 pathway." (PMID 26550019, 2015). "All these results indicated that PL might alleviate CCl4-induced hepatic fibrosis via the EGFR/STAT3 signaling pathway." (PMID 26550019, 2015). "Experiments displayed that in the hepatic fibrosis mice model with POFUT1 knockout in LSECs, POFUT1 deficiency inhibited the KLF2-eNOS-sGC signaling axis, promoting injury-induced LSEC capillarization, while up-regulating the expression of fibrinogen in LSEC through the NOTCH/HES1/STAT3 pathway." (PMID 40761743, 2025). "Therefore, we hypothesized that STAT3 might be the direct target of Ssb1 for the treatment of liver fibrosis." (PMID 41163803, 2025). "This activation triggers HSC transformation into myofibroblasts, inhibiting ECM degradation.Molecular docking simulations suggest that ginsenoside Rh2—a bioactive constituent of PZH—may attenuate hepatic fibrosis through modulation of the EGFR/JAK1/STAT3 signaling axis." (PMID 41181146, 2025). "However, the precise role of STAT3 in liver fibrosis remains debated." (PMID 40852727, 2025). "Moreover, we predicted that narcissin from BR, casuarictin from PRA, and γ-sitosterol from BR and ZRR, are the active compounds in XYS responsible for its therapeutic effect on NASH-related liver fibrosis, through targeting STAT3, NFκB, and PPARγ, respectively." (PMID 39338294, 2024). "Therefore, nicotine through the miRNA-124/ STAT-3 pathway may have a possible anti-inflammatory role in liver fibrosis by activating the cholinergic anti-inflammatory pathway." (PMID 38549169, 2024). "Other possible mechanisms for the protective role of niclosamide may be associated with the suppression pathway of Wnt/beta-catenin, NF-kappaB, signal transducer and activator of transcription 3 and notch signals which was validated in targeting cancer and liver fibrosis." (PMID 37514136, 2023). "Our results suggest that Saffron inhibits the activation of HSCs by JAK/STAT3 signaling pathway, thereby alleviating liver fibrosis in mice, laying a theoretical foundation for finding new therapeutic methods and drugs to improve the clinical outcomes of patients with liver fibrosis in the future." (PMID 38055395, 2023). "Therefore, it was speculated that the inhibitory effect of AHWE on liver fibrosis was related to the activation of the STAT3 signaling pathway." (PMID 36588728, 2022).